OCLN (occludin)
Diseases named in the same sentence as OCLN in open-access papers (continued):
Sharing a sentence is not in itself a finding about the gene and the disease.
lung adenocarcinoma (8 papers, 2013 to 2025). A carcinoma that arises from the lung and is characterized by the presence of malignant glandular epithelial cells. "CLDN1 was a transcriptional activator of OCLN, and was also reported as not only a metastasis suppressor but also a possible prognostic predictor for lung adenocarcinoma." (PMID 24369726, 2013). "OCLN may function as paracellular barrier to large molecules in chemoresistant lung adenocarcinoma cells." (PMID 30310131, 2018). "In addition, that of OCLN was increased by resistance to CDDP in human lung adenocarcinoma RERF-LC-MS and PC-3 cells." (PMID 30310131, 2018). "In our studies, we demonstrate, for the first time, the effect of melatonin on the migration of human lung adenocarcinoma A549 cells and observed an association between JNK/MAPK pathway and the expression of tight junction (TJ) related proteins occludin, OPN and MLCK." (PMID 24992189, 2014). "OCLN may be not directly implicated in the acquisition of resistance to anticancer drugs in lung adenocarcinoma cells, but it suppresses chemosensitivity in spheroid cells." (PMID 30310131, 2018). "Similarly, the increase in OCLN mRNA was also observed in CDDP-resistant RERF-LC-MS and PC-3 cells, indicating that the induction of OCLN may commonly occur in chemoresistant lung adenocarcinoma cells." (PMID 30310131, 2018). "The mRNA level of occludin (OCLN), a tight junctional protein, was increased in the cisplatin (CDDP), doxorubicin (DXR), 7-ethyl-10-hydroxy-camptothecin, or gemcitabine-resistant human lung adenocarcinoma A549 cells." (PMID 30310131, 2018). "However, the pathophysiological role of OCLN in lung adenocarcinoma tissue has not been clarified yet." (PMID 30310131, 2018).
melanoma (8 papers, 2013 to 2025). A malignant, usually aggressive tumor composed of atypical, neoplastic melanocytes. "We can conclude that down-regulation of occludin expression in the patients with melanoma is a hallmark of cancer progression and it might be used as a prognostic factor." (PMID 31754355, 2019). "We can conclude that low expression of occludin in the patients with melanoma is a hallmark of cancer progression and may be used as a prognostic factor." (PMID 31754355, 2019). "These differ in their fusion endpoints from the OCLN–RASGRF1 and IQGAP1–RASGRF1 fusions reported here from a cholangiocarcinoma and a melanoma, respectively (although the segment of OCLN in both OCLN–RASGRF1 fusions is the same)." (PMID 40615519, 2025). "The occludin expression level reduced five-fold in the melanoma patients compared to the control group (P=0.000)." (PMID 31754355, 2019). "Recombinant S100A9, a calcium-binding protein A9, which is known as migration inhibitory factor has been shown to reduce the A-375 melanoma cell line proliferation and down-regulate OCLN gene expression in a time- and dose-dependent manner." (PMID 31754355, 2019). "In our present study, down-regulation of occludin mRNA was markedly observed in the melanoma as compared to the normal tissues." (PMID 31754355, 2019). "Occludin mRNA expression level was 0.19±0.256 lower in melanoma patients than in the normal samples." (PMID 31754355, 2019). "The occludin mRNA level was compared between paraffin-embedded tissues of 40 patients with melanoma and 10 subjects with normal skin." (PMID 31754355, 2019). "The aim of this study was to determine occludin expression level and its correlation with clinicopathological features of the patients with melanoma." (PMID 31754355, 2019). "In the present study, the occludin mRNA expression level reduced five-fold in the melanoma patients compared to the normal group." (PMID 31754355, 2019). "Although recent studies provide sufficient evidence supporting the functional importance of occludin in cancer, the prognostic significance of occludin expression levels in melanoma remains obscure." (PMID 31754355, 2019). "The occludin mRNA level reduced five-fold in the melanoma patients compared to the control group (P=0.000)." (PMID 31754355, 2019). "Based on our knowledge, this is the first report on occludin gene expression in the patients with melanoma." (PMID 31754355, 2019). "Thus, the aim of this study was to determine occludin expression level and its correlation with clinicopathological features of the patients with melanoma." (PMID 31754355, 2019). "Also, there is no information on the role of occludin expression in melanoma." (PMID 31754355, 2019).
schizophrenia (8 papers, 2016 to 2024). A major psychotic disorder characterized by abnormalities in the perception or expression of reality. "On the other hand, the level of occludin has been found to be elevated corresponding to inflammation in human postmortem brain tissue in schizophrenia." (PMID 36980071, 2023). "Higher levels of OCLN have been observed in patients with bipolar disorder, autism spectrum disorder, and schizophrenia compared to healthy individuals." (PMID 38002705, 2023). "Tight junction proteins such as CDH5 and OCLN that contribute to BBB integrity were found to be elevated in relation to inflammation in postmortem tissue in schizophrenia." (PMID 30214039, 2020). "The “high inflammation” schizophrenia subgroup had lower ABCG2 and higher ICAM1, VE-cadherin, occludin and interferon-induced transmembrane protein mRNAs compared to both “low inflammation” schizophrenia and “low inflammation” control subgroups." (PMID 30214039, 2020). "Schizophrenia patients with deficit syndrome (i.e. severe negative and cognitive symptoms) can be expected to have unhealthy dietary habits, which could explain the association with IgM response to occludin." (PMID 35506416, 2022). "Authors also reported an increased ratio of IgM towards components of the paracellular route (zonulin + occludin)/components of the transcellular route (talin + actin + vinculin) in deficit v. non-deficit schizophrenia and in schizophrenia v. controls." (PMID 35506416, 2022).
brain tumors (7 papers, 2014 to 2025). "The perioperative serum occludin level is associated with the severity of peritumoral/pericavity edema in patients with brain tumors." (PMID 32884584, 2020). "Further studies are needed to clarify the mechanisms underlying BBB damage and alterations in brain tumor levels of occludin." (PMID 32884584, 2020). "Compared with healthy controls, the serum occludin level was higher in patients with brain tumors both preoperatively and postoperatively (P < 0.001)." (PMID 32884584, 2020). "We found that the serum level of occludin was significantly higher in patients with brain tumors, both before and after surgery, than in healthy people." (PMID 32884584, 2020). "The TJ leaks of human brain tumors Microvessels are responsible for cerebral edema in certain types of brain cancer, which is an excellent example of down-regulation of occludin in cancer." (PMID 24992189, 2014). "Metastatic brain tumors are known to have a disrupted inter-endothelial tight junction due to the downregulation of tight junction components, including claudin-1, claudin-5, and occludin." (PMID 34722268, 2021). "The serum occludin level could potentially be used as a biomarker for perioperative cerebral edema in patients with brain tumors." (PMID 32884584, 2020). "The present study found that the serum occludin level was increased in patients with brain tumors as compared with healthy controls, suggesting that tumor-induced damage to the BBB during the perioperative period may lead to the loss of occludin from the BBB." (PMID 32884584, 2020). "However, both the preoperative and postoperative serum occludin levels in patients with brain tumors were significantly higher than the levels in healthy people." (PMID 32884584, 2020). "Although some studies have shown an association between downregulated or degraded OCLN and damaged BBB function, these markers of BBB disruption have not been previously evaluated in the context of radiotherapy (and RT-related side effects) in patients with brain tumours." (PMID 38337823, 2024). "Therefore, we hypothesized that the occludin level in peripheral blood might serve as a biomarker for cerebral edema due to BBB damage in patients with brain tumors." (PMID 32884584, 2020). "In addition, this is the first clinical study to provide data on serum concentrations of OCLN, CLN5, and Zo-1 in patients with brain tumours during IMRT." (PMID 38337823, 2024). "It is possible that MMP activation may be a major mechanism by which degradation of occludin and damage to the BBB occur in patients with brain tumors." (PMID 32884584, 2020). "Previous studies have shown that peritumoral brain edema is associated with a low content of occludin in the tumor, but it has not been clarified whether the low content of occludin in the BBB of brain tumors is mainly due to degradation or low expression of occludin." (PMID 32884584, 2020). "However, no previous investigations have reported whether occludin is degraded and released into the bloodstream because of damage to the BBB by a brain tumor or brain surgery." (PMID 32884584, 2020).
C. perfringens infection (7 papers, 2018 to 2025). "In the present study, C. perfringens infection decreased the mRNA expression levels of Claudin-1 and Occludin genes in the ileum." (PMID 37138630, 2023). "C. perfringens infection significantly downregulated the mRNA expression of occludin and claudin-1 in the small intestine, as reported in previous studies." (PMID 34712727, 2021). "Clostridium perfringens infection increased the expression of occludin, ZO-1, GLP2, OGG1 and TFF2 genes (P < 0.001) in the wall of the ileum." (PMID 32264939, 2020). "C. perfringens infection significantly decreased the OCLN mRNA expression (P < 0.05), while L. acidophilus treatment tended to decrease MUC2 mRNA expression in the jejunum (P = 0.082)." (PMID 29599973, 2018). "Notably, C. perfringens infection significantly reduced (p < 0.05) the expression of Claudin-1 and Occludin genes, while the 40 and 120 mg Zn groups alleviated the decrease in Claudin-1 expression." (PMID 40559850, 2025). "The tight junction-related genes (ZO-1, Occludin, Claudin1, and MUC2) in the jejunum down-regulated significantly (P < 0.05) in all C. perfringens infection groups compared to Control group." (PMID 35769317, 2022). "In the present study, the expression of occludin, ZO-1, GLP2, OGG1 and TFF2 genes increased in the wall of the small intestine, which indicates that C. perfringens infection in turkeys compromised intestinal barrier integrity." (PMID 32264939, 2020). "The expression of occludin, ZO-1, GLP2, OGG1 and TFF2 genes increased in the wall of the ileum (P < 0.001) in response to C. perfringens infection." (PMID 32264939, 2020).
Cognitive impairment (7 papers, 2013 to 2025). Abnormal cognition is characterized by deficits in thinking, reasoning, or remembering. "We and others have previously reported that high salt exacerbates cognitive impairment, and BBB leakage, with decreased gene expression of TJ associated proteins such as occludin, claudin-5 and zona occluding." (PMID 24339994, 2013). "However, future studies are required to clarify how occludin is involved in the pathophysiology of cognitive impairment in ADHD." (PMID 36980071, 2023). "We also found a positive correlation between occludin levels and detectability in the CPT, indicating that gut leakage markers may not only be associated with vulnerability to ADHD, but also associated with its cognitive deficit, inattentiveness." (PMID 36980071, 2023). "Our recent in vivo experiments tested with e-Cig vape (0% or 1.8% nicotine) showed reduced expression of critical genes in the mouse brain, diminished the expression of occludin and glucose transporter 1 (Glut1) proteins, and increased BBB permeability, neuroinflammation, and cognitive impairment." (PMID 35883819, 2022).
glioblastoma (7 papers, 2012 to 2025). The most malignant astrocytic tumor (WHO grade IV). "Western blot was applied to evaluate expression of N-cadherin, Slug, β-catenin and p-4E-BP1, which disclosed obviously reducing of these proteins in hsa_circ_0021205 knock-down glioblastoma cells, while Occludin level elevated." (PMID 38341418, 2024). "As Occludin and Claudin-5 are the anchors of transendothelial cell permeability, the mechanism by which glioblastoma U-87 cells decreased the resistance of the bEnd.3 monolayer was investigated in the current study." (PMID 35053392, 2022). "We found that the expressions of Claudin 1 and Occludin were significantly decreased in glioblastoma cells after treatment of TGF-β." (PMID 33613746, 2021). "The claudin-1 expression is lost in the microvessels of glioblastoma multiform, whereas claudin-5 and occludin are significantly down-regulated, and ZO-1 expression is unaffected." (PMID 33208141, 2020). "Besides, protein level of N-cadherin, Slug, β-catenin and p-4E-BP1 was positively correlated with HSL expression, while Occludin was negatively associated with HSL expression, suggesting downregulation of HSL weakened EMT processes of glioblastoma." (PMID 38341418, 2024). "Besides, in HSL-overexpression rescued glioblastoma cells, partially upregulation of Occludin and downregulation of N-cadherin, Slug, β-catenin and p-4E-BP1 can be observed." (PMID 38341418, 2024). "Besides, decreased level of N-cadherin, Slug, β-catenin and p-4E-BP1 expression can be observed in Western blot after miR-195-5p overexpression in glioblastoma cells, with increased Occludin expression level." (PMID 38341418, 2024). "Interestingly, our data corroborate a recent report suggesting that CatS inhibition restores the turnover of tight junction proteins including occludin of human glioblastoma cell lines." (PMID 36670867, 2022). "Also, the selective loss of claudin-3 or occludin was observed in experimental allergic encephalomyelitis (EAE) and glioblastoma multiform (GBM) resulting in a loss in BBB integrity along with some functional barrier loss." (PMID 33208141, 2020).
liver disease (7 papers, 2012 to 2025). "The TJ proteins CLDN1 and OCLN on the basolateral membrane of hepatocytes serve as entry factors for HCV—a major cause of liver disease and cancer worldwide." (PMID 32012812, 2020). "Tight junction proteins, including occludin and Zo-1, are important markers of the intestinal barrier and are becoming targets for new therapeutic approaches to liver disease." (PMID 38999886, 2024). "Besides the secretion of bile and gastric juice decrease, liver cirrhosis-related portal hypertension can decrease the expression of occludin and claudin-1, both of which participate in the integrity of the mucosal." (PMID 38287258, 2024). "Decreased expression of occludin and claudin-1 in the duodenal mucosa have also been reported in cirrhosis and their expression levels correlated with LPS concentrations, severity of liver disease and portal hypertension (esophageal varices)." (PMID 34513903, 2021).
microcephaly (7 papers, 2017 to 2025). A congenital or acquired developmental disorder in which the circumference of the head is smaller than normal for the person's age and sex. "It is reported that the mutation of Occludin (OCLN) can lead to microcephaly and cortical malformation in humans." (PMID 36118578, 2022). "Specifically, we show that loss of full-length OCLN in the mouse embryonic cortex leads to microcephaly due to prolonged M-phase, a transient burst of apoptosis, and precocious neuronal differentiation at the expense of the progenitor pool." (PMID 31794381, 2019). "In humans, various OCLN mutations lead to microcephaly, brain calcification and renal disease." (PMID 40661615, 2025). "OCLN mutations in human patients can lead to microcephaly and band-like calcifications with polymicrogyria characterized by loss of cortical convolutions, shallow or absent sulci, and multiple small gyri giving the cortex surface a roughened irregular appearance." (PMID 31783547, 2019). "Occludin (OCLN) mutations cause human microcephaly and cortical malformation." (PMID 31794381, 2019). "In this study, we use human and mouse models of corticogenesis to explore the role of OCLN in the developing cortex, specifically to investigate its potential interaction with the centrosome and elucidate mechanisms through which its loss-of-function produces microcephaly." (PMID 31794381, 2019). "These defects are consistent with observed microcephaly and PMG associated with human OCLN mutations." (PMID 31794381, 2019). "Recessive mutations in the OCLN gene (MIM#251290) also named pseudo-TORCH syndrome, cause microcephaly with band–like calcifications, simplified gyral pattern and polymicrogyria." (PMID 28460636, 2017). "Interestingly, mutations in other TJ protein-encoding genes such as JAM3 produce brain hemorrhage rather than the congenital microcephaly and PMG associated with the OCLN mutation phenotype in humans, suggesting that OCLN may have developmental functions unanticipated for a TJ protein." (PMID 31794381, 2019).
atherosclerosis (6 papers, 2020 to 2026). A disease characterized by the build-up of fatty material and calcium deposition in the arterial wall resulting in partial or complete occlusion of the arterial lumen. "In conclusion, our results showed that T3SS induces intestinal barrier damage by promoting ferroptosis and reducing the expression of occludin and ZO‐1 in intestinal epithelial cells, thereby aggravating atherosclerosis progression in T2D‐AS mice." (PMID 39807021, 2025). "A cell experiment found that asiatic acid reduced atherosclerosis by inhibiting the redistribution of occludin and zona occludens -1(ZO-1)." (PMID 33013406, 2020). "The expression levels of claudin-5, ZO-1, and occludin are decreased in the cerebral microvessels of mice fed a high-fat diet, indicating that the combined effects of diet and cadmium exposure accelerate the development and progression of atherosclerosis." (PMID 39456818, 2024). "In addition, the expression of tight junction proteins (claudin-1, occludin, and ZO-1) was significantly downregulated in atherosclerosis mice, indicating that the tight junctions structure was disrupted and that the tight junctions structure was disrupted." (PMID 36034838, 2022).
colorectal adenocarcinoma (6 papers, 2017 to 2025). The most common type of colorectal carcinoma. "In colorectal adenocarcinoma, reduced occludin staining was associated with advanced pT stage (p < 0.0001), L1 status (p = 0.0384), and absence of microsatellite instability (p < 0.0001)." (PMID 40173205, 2025). "In vitro experiments showed that rTsNas14 can down-regulate the expression of occludin and claudin-1 proteins of human colorectal adenocarcinoma (Caco-2) cells and improve the permeability of an intestinal barrier model." (PMID 40839561, 2025). "Their investigation showed a reduced expression of occludin and ZO-1 in poorly differentiated gastric and colorectal adenocarcinoma." (PMID 30140423, 2018). "Sat in colorectal adenocarcinoma Caco-2 cells induces redistribution of the ZO1, ZO3 and occludin proteins leading to an increase in intercellular permeability." (PMID 32084148, 2020).